SNORD114-24 (small nucleolar RNA, C/D box 114-24)
Synonyms: 14q(II-24)
Gene: Small nucleolar RNA gene on chromosome 14 (100,984,777 to 100,984,848, forward strand). Ensembl gene ENSG00000201899.
Gene Ontology:
Biological process: RNA processing
Cellular component: nucleolus
Homologues: Orthologues: chimpanzee SNORD114-24 (97% identical), mouse Gm22205 (68% identical). Paralogues in human: SNORD114-9 (83% identical), SNORD114-20 (82% identical), SNORD114-28 (82% identical), SNORD114-15 (81% identical), SNORD114-22 (81% identical), SNORD114-23 (81% identical), SNORD114-26 (81% identical), SNORD114-21 (79% identical), SNORD114-25 (79% identical), SNORD114-29 (79% identical), SNORD114-5 (75% identical), SNORD114-10 (74% identical), and 26 more.